MMP13 (matrix metallopeptidase 13)
Diseases named in the same sentence as MMP13 in open-access papers (continued):
Sharing a sentence is not in itself a finding about the gene and the disease.
multiple myeloma (14 papers, 2014 to 2025). "Others have described homophilic interactions between VISTA expressed by apoptotic cells and macrophages as well as a role for osteoclast-expressed VISTA as a receptor for MMP-13 in the context of myeloma-associated osteolysis." (PMID 39482534, 2024). "Mmp13 null mice are resistant to the loss of bone mass caused by multiple myeloma, though the number of osteoclasts on bone was unaffected by the MMP13 deletion." (PMID 35715555, 2022). "Our findings identify a role of PD-1H in bone biology independent of its known immunoregulatory functions and suggest that targeting the MMP-13/PD-1H axis may represent a potential approach for the treatment of myeloma associated osteolysis." (PMID 37460553, 2023). "In contrast, no such co-expression was observed in the NC group, further supporting the role of MMP13 secreted by myeloma cells in facilitating osteoclast activity." (PMID 39915476, 2025). "In the context of multiple myeloma, in which MMP-13 can be highly expressed by malignant cells, this MMP-13/VISTA signaling axis can mediate excessive osteoclast activation and the development of osteolytic bone disease." (PMID 39482534, 2024). "Further, in the 5TGM1 MM bone disease mouse model, silencing MMP-13 expression in myeloma cells inhibits the development of osteolytic lesions." (PMID 37460553, 2023). "As such, this study identified a critical role for PD-1H in OCL formation and MMP-13-mediated bone resorption in multiple myeloma." (PMID 37460553, 2023). "To determine the role of MMP-13/PD-1H in the development of myeloma-induced lytic bone lesions, we developed an intratibial MM bone disease model using Pd-1hwtRag2-/- mice that recapitulates myeloma tumor growth coupled with severe osteolysis." (PMID 37460553, 2023). "MMP-13-mediated release of VEGF-C increased cancer cell spreading through lymphatic vascular systems in paediatric multiple myeloma." (PMID 35805035, 2022). "Another study showed that myeloma-derived MMP13 regulates the fusion of osteoclasts and bone resorption." (PMID 35281094, 2022). "Injection of MMP-13-selective inhibitor Zn2+-chelating compound, which targets the catalytic domain of MMP-13, significantly reduced the level of bone destruction and delayed MM growth in an immunocompetent syngeneic mouse model with multiple myeloma." (PMID 35805035, 2022). "Matrix metalloproteinase 13 (MMP13) is secreted by multiple myeloma cells and induces osteoclast active factors produced by multiple myeloma cells." (PMID 31781601, 2019). "From this perspective, our findings may lead to novel therapeutic strategies to treat both MM bone disease and overcome myeloma-induced immunosuppression by targeting the MMP-13/PD-1H axis." (PMID 37460553, 2023). "Interestingly, the action of MMP13 in myeloma results from its ability to promote osteoclast fusion by up-regulating the fusogen DC-STAMP, independently of its enzymatic activity." (PMID 35715555, 2022). "Notably, multiple myeloma-derived MMP13 promoted the fusion of osteoclasts originated from mouse bone marrow cells in the presence of M-CSF and RANKL, proposing a role of exogenous collagenase." (PMID 32370054, 2020). "Studies have shown that the core protein of serglycin from myeloma cells can bind to proteases like MMP-9 (matrix metalloproteinase-9) and MMP-13." (PMID 29088739, 2017). "This review focuses on the role of MMP-1, MMP-2, MMP-7, MMP-9, MMP-13, MMP-14, and MMP-15 and the four types of TIMPs in the invasion of myeloma cells, angiogenesis, osteolytic osteopathy, to offer some novel perspectives on the clinical diagnostics and therapeutics of MM." (PMID 37823051, 2023). "We hypothesize that this lack of correlation arises because MMP13 in myeloma cells is primarily induced by CXCL7, whereas MYC, involved in various cancer pathways, is regulated by multiple mechanisms." (PMID 39915476, 2025).
Obesity (14 papers, 2010 to 2025). Accumulation of substantial excess body fat. "This is consistent with alterations in MMP-13 expression as in OA cases resulting from other causes, such as aging, obesity, joint misalignment, and acute injury." (PMID 29971011, 2018). "In addition, the BMI-dependent effect of leptin for the expression of TIMP-2 and MMP-13 may explain why obesity is associated with an increased risk for OA." (PMID 20534145, 2010). "With regard to BMI, patients with class II + III obesity demonstrated a higher MMP13 mRNA expression level in the synovium than those with class I obesity; however, their level was lower than that in overweight patients." (PMID 40004793, 2025). "MMP13 expression is relatively higher in ScWAT than GWAT under standard diet, while this profile is inverted under a HFD with an approximately four-fold expression in GWAT compared to ScWAT, suggesting a contribution of MMP13 in the pathogenesis of obesity." (PMID 37445827, 2023). "Obesity causes the rise of various inflammatory cytokines and matrix metalloproteinases (MMP) such as interleukin (IL)-1 β, IL-6, MMP-1, MMP-6 and MMP-13." (PMID 38033821, 2023). "Remarkably, ST36+GB34-treated obese rats were almost completely rescued from the deleterious effect of obesity, with more effectiveness in preventing cartilage loss and reducing the total Mankin score and the expression of MMP-1 and MMP-13." (PMID 32724821, 2020). "The situation appears to be most exacerbated in cases of extreme obesity where a strong positive correlation exists between the responsiveness of the MMP-13 gene to leptin and the BMI of osteoarthritic individuals." (PMID 29971011, 2018). "Both Mmp12 and Mmp13 have been recently shown to be elevated in the liver in other models of diet induced obesity as well." (PMID 25880591, 2015). "Mmp2, 3, Mmp12 and Mmp13 are reportedly positively correlated with the degree of obesity and were up-regulated in the visceral WAT of HFD fed mice." (PMID 22947075, 2012). "Since we found that SREBP-2 was associated with BMI and as obesity is characterized by upregulated cholesterol synthesis we evaluated the effect of sterols on SREBP-2 expression and chondrocytes markers such as MMP-13 and COL2A1." (PMID 22662110, 2012). "Hence, pharmacological inhibition of MMP13 may prove efficient against obesity and its complications." (PMID 37445827, 2023). "Regarding the BMI, the highest expression level of MMP13 mRNA in OA-affected articular cartilage with subchondral bone was observed in overweight patients; the level of expression was lower in patients with class I obesity and was the lowest in patients with class II + III obesity." (PMID 40004793, 2025). "However, the MMP13 mRNA expression level in cartilage was found to be negatively related to the degree of obesity." (PMID 40004793, 2025). "Moreover, MMP13 mRNA expression levels are correlated with the degree of obesity in GWAT but not in ScWAT, underscoring the prominent role of MMP13 in the development of visceral obesity." (PMID 37445827, 2023). "Interestingly, MMP13 is more expressed in the stromal vascular fraction (SVF) than in adipocytes and this expression is exacerbated in the SVF in both GWAT and ScWAT under a HFD, implying the role of MMP13 in adipose tissue and ECM remodeling during obesity." (PMID 37445827, 2023).
pancreatic cancer (13 papers, 2013 to 2025). "Of these, the expression of several matrix metalloproteinases was decreased, including Mmp10, Mmp12, and Mmp13; these metalloproteinases have been implicated in epithelial-to-mesenchymal transition, invasion, and metastases in pancreatic cancer." (PMID 41373844, 2025). "Leptin induces cell migration, invasion, and metastasis in an orthotopic model of pancreatic cancer, and the simultaneous increase in the expression of leptin receptor and MMP13 also shows a positive association with the TNM stage." (PMID 33804101, 2021). "Although MMP-13 has been suggested to be linked to the metastatic potential of pancreatic cancer via immunohistochemistry analysis and cDNA array assay, this has never been proven experimentally." (PMID 25948792, 2015). "Research has linked these genes to apoptosis: HGF inhibits anoikis in pancreatic cancer cells via the PI3K pathway, and MMP13 reduces anoikis through neural/neuroglial antigen 2 (NG2) shedding." (PMID 40014587, 2025). "In human 3D cancer co–cultures, however, Akt inhibition did not impact CD11c+/CD206+ populations, while a notable reduction to MMP13 production was observed only in pancreatic cancer co–cultures." (PMID 39211033, 2024). "The translational value of MMP-13 in the diagnosis, prognosis and treatment of pancreatic cancer is definitely worth further exploration." (PMID 25948792, 2015). "We further used the MMP-13 inhibitor CL82198 to confirm that leptin's action on the pancreatic cancer cells was mediated by MMP-13." (PMID 25948792, 2015). "We demonstrated that the leptin receptor Ob-Rb is present in pancreatic cancer cells, and the activation of Ob-Rb can enhance the invasion of pancreatic cancer via upregulating MMP-13 production." (PMID 25948792, 2015). "In conclusion, this study elucidates the role of the IFN-γ/JAK/STAT1/CCL2/MMP13 pathway in exerting antitumor effects in pancreatic cancer by activating immune cells, which challenges the conventional understanding of CCL2 and MMP13 as promoters of tumor progression." (PMID 40909948, 2025). "To investigate whether MMP-13 can increase the mobility of pancreatic cancer cells in vitro, we overexpressed MMP-13 in PANC-1 cells (PANC-1-MMP13) using lentiviral vectors." (PMID 25948792, 2015). "Another novel finding of this study is that MMP-13 may play an important role in leptin-induced pancreatic cancer metastasis." (PMID 25948792, 2015). "Our findings suggest that leptin enhances the invasion of pancreatic cancer through the increase in MMP-13 production, and targeting the leptin/MMP-13 axis could be an attractive therapeutic strategy for pancreatic cancer." (PMID 25948792, 2015). "Taken together, our data suggest that MMP-13 may serve as a downstream effector of the leptin -JAK2/STAT3 cascade responsible for pancreatic cancer cell invasion." (PMID 25948792, 2015). "Furthermore, in human pancreatic cancer tissues, the expression of Ob-Rb was positively correlated with the MMP-13 level." (PMID 25948792, 2015). "In addition, in both mouse transplanted pancreatic cancer and human clinical pancreatic cancer tissues, we observed a correlation between Ob-Rb and MMP-13." (PMID 25948792, 2015). "Therefore, the conclusion that leptin regulates MMP-13 in pancreatic cancer is solid." (PMID 25948792, 2015). "Investigations into pancreatic cancer have revealed that both CCL2 and MMP13 are regulated by the upstream IFN-γ/STAT1 signaling, which facilitates macrophage polarization." (PMID 40909948, 2025). "Leptin upregulates the expression of matrix metalloproteinase-13 (MMP-13) through the JAK2/STAT3 signaling pathway and enhances the invasion ability of pancreatic cancer cells." (PMID 34485124, 2021). "To further understand the relationship between the leptin/MMP-13 axis and human pancreatic cancer development, we performed immunohistochemical staining of Ob-Rb and MMP-13 in 60 pancreatic cancer tissue samples." (PMID 25948792, 2015).
pancreatic cancer (continued). "To understand whether and which types of MMPs were involved in the pancreatic cancer cell invasion triggered by leptin, we analyzed the expression change of MMP-2, MMP-7, MMP-9 and MMP-13 before and after leptin treatment." (PMID 25948792, 2015). "In the present study, we compared the expression levels of MMP-2, MMP-7, MMP-9 and MMP-13 in pancreatic cancer cells with and without leptin treatment." (PMID 25948792, 2015).
synovitis (13 papers, 2014 to 2025). Inflammation of a synovial membrane. "In knee OA synovium with severe synovitis, increased IL-34 mRNA expression was directly associated with IL-6, IκB, NF-κB, and MMP-13, in addition to knee OA FLS." (PMID 32409720, 2020). "In the middle and deep layers, MMP13 was scattered in the cells, and distributed in cells and matrix in the surface layer, which was consistent with synovitis." (PMID 36168980, 2022). "A previous report has indicated that FA had the ability to decrease the levels of hydrogen peroxide-induced IL-1β, TNF-α, MMP-1, and MMP-13, thereby reducing bone destruction, synovitis, and the erosion of cartilage in antigen-induced arthritis." (PMID 24883069, 2014). "MMP13, which is upregulated in the joint by IL-1 and TNF, leading to articular cartilage destruction and synovitis, is widely studied as a promising target for several DMOAD candidates due to its OA-specific properties." (PMID 39408977, 2024). "After applying with synovitis ointment, the expression levels of SDF-1, CXCR4, MMP-9, and MMP-13 reduced significantly in KOA rats." (PMID 35815270, 2022). "To unravel the effects of synovitis ointment on SDF-1/CXCR4, we examined the expression of SDF-1, CXCR4, MMP-9, and MMP-13 in serum under different treatment conditions through the ELISA method." (PMID 35815270, 2022). "Compared with the KOA group, the synovitis ointment group, the KOA + Western medicine group, and the KOA + Chinese medicine group significantly decreased the expression of SDF-1, CXCR4, MMP-9, and MMP-13." (PMID 35815270, 2022). "Alternatively, NF-κB and MMP-13 mRNA expressions were found to be higher in knee OA synovium with severe synovitis than that in those with mild and no synovitis, but these differences were not statistically significant." (PMID 32409720, 2020). "Synovitis in idiopathic OA may elicit the SDF-1 and MMP-13 signaling pathways, among others, similar to those activated with post-traumatic OA and in combination with age-related changes in proteoglycan turnover, collagen, and vascular changes." (PMID 29284451, 2017). "Although bevacizumab did not decrease IL1B expression significantly, we suggest that the decrease in MMP13 and ADAMTS5 expression levels contributed to the absence of synovitis." (PMID 25230745, 2014).
glioblastoma (11 papers, 2013 to 2025). The most malignant astrocytic tumor (WHO grade IV). "It has also been suggested that the highly invasive potential of CSCs depends on MMP-13 enzymatic activity in glioblastoma." (PMID 31726667, 2019). "For instance, glioblastoma CSCs express MMP-13 to enhance migration whereas knockdown of MMP-13 reduced migratory and invasive capacity of these CSCs." (PMID 28148265, 2017). "Inoue A, Takahashi H, Harada H, Kohno S, Ohue S, Kobayashi K, Yano H, Tanaka J, Ohnishi T: Cancer stem-like cells of glioblastoma characteristically express MMP-13 and display highly invasive activity." (PMID 27454254, 2016). "The identified DEGs contain biomarkers as MMP13 that is known to be expressed in cancer stem-like cells of glioblastoma where it correlates with cell invasiveness." (PMID 27454254, 2016). "Even when correlating glioblastomas versus astrocytomas, we showed a significantly increased level of MMP1, MMP3, MMP13, and TIMP1." (PMID 38474106, 2024). "Similar dose- and oxygen status-dependent effects on MMP-13 mRNA expression were also detected in the human D54MG and U373MG glioblastoma cell lines." (PMID 24273604, 2013).
hepatocellular carcinoma (11 papers, 2010 to 2025). A malignant tumor that arises from hepatocytes. "Overexpression of miR-127 inhibits hepatocellular carcinoma cell migration, invasion and tumor growth through repressing MMP13 expression and diminishing MMP13/TGFβ-induced cell migration." (PMID 32979257, 2020). "It has been reported that MMP13 is related to cancer aggressiveness in hepatocellular carcinoma." (PMID 27356745, 2016).
joint disease (11 papers, 2008 to 2025). "As a next step in evaluating the causality of PLR suppression in joint disease, we generated mice with a targeted deletion of MMP13 from osteocytes." (PMID 31700695, 2019). "The current findings, in which cartilage degeneration results from osteocyte-intrinsic ablation of PLR enzyme MMP13, strengthen the idea that osteocytes play a causal role in joint disease through PLR." (PMID 31700695, 2019). "MMP-1 and MMP-13 are closely related to cartilage collagen dissolution, which is a key protein hydrolysis event in joint diseases that is essentially irreversible." (PMID 33995548, 2021). "The inhibition of matrix metalloproteinase MMP-13 is a validated strategy to prevent the progression of this common joint disorder." (PMID 34576138, 2021). "MMP13 activity in chondrocytes and synovial cells appears to be critical in cartilage formation and in joint diseases." (PMID 23723167, 2013). "Therefore, maintaining an appropriate OPG/RANKL ratio and controlling MMP-13 activity are crucial for preserving cartilage health and preventing the development of bone and joint diseases." (PMID 39430588, 2024). "Moreover, in Ctsk(-/-) knockout mice with OA induced by joint instability, disease progression was significantly delayed, while the expression levels of other proteases (such as MMP13 and ADAMTS5) decreased compared to the control group." (PMID 36233118, 2022). "Although many questions remain about the role and regulation of PLR in OA, our data collectively suggest that osteocyte MMP13 dynamically maintains subchondral bone homeostasis and joint crosstalk, and that its disruption can exacerbate joint disease, likely through suppression of PLR." (PMID 31700695, 2019). "As a step toward evaluating the causality of PLR suppression in joint disease, we evaluated the bone and joint phenotypes of a novel mouse model with ablation of the critical PLR enzyme MMP13 from osteocytes, but not chondrocytes." (PMID 31700695, 2019). "A major goal should be to identify compounds targeting MMP13 without interfering with other MMPs, not only for the previously suggested treatment of joint diseases, but as shown by our data also for the treatment of pathologies such as sepsis and IBD." (PMID 23723167, 2013). "Molecular modifications that affect the activity of MMP-13 or RUNX2 could change the abnormal function not only of cartilage but also meniscus, facing OA as a whole-joint disease and not as a cartilage disease." (PMID 40724902, 2025).